EFNB3 (ephrin B3)
Diseases named in the same sentence as EFNB3 in open-access papers (continued):
Sharing a sentence is not in itself a finding about the gene and the disease.
tumor (14 papers, 2012 to 2025). "Likewise, ephrin-B3 seems to negatively impact Central Nervous System neoplasia, with its expression in gliomas reported 2.5-fold higher in tumor samples compared with controls and linked to higher grade tumors." (PMID 34445116, 2021). "In GBM, elevated ephrin-B3 expression suppresses this pro-apoptotic signal, promoting the survival of both tumor and endothelial cells." (PMID 41200151, 2025). "Silencing ephrin-B3 reduces angiogenesis and tumor growth, highlighting the therapeutic potential of disrupting the EphA4/ephrin-B3 axis." (PMID 41200151, 2025). "Lastly, we provide evidence that in GBM, Ephrin-B3 favors tumor growth by inhibiting EphA4-induced endothelial cell death and we then propose to use this trait in a therapeutic perspective." (PMID 28423606, 2017). "Mean ratios of peripheral tumor vessels to tumor volumes is decreased in 5 EFNB3 silenced grafts as compared to 6 size-matched control ones, ranging from 11.75 ± 6.00% to 6.22 ± 3.86% respectively." (PMID 28423606, 2017). "Lastly, silencing of Ephrin-B3 decreases tumor vascularization and growth in a xenograft mice model." (PMID 28423606, 2017). "Here, we report that Ephrin-B3 is highly expressed in human biopsies and that it inhibits EphA4 pro-apoptotic activity in tumor cells." (PMID 28423606, 2017). "EphA2 Ser897 was previously shown to drive migration propensity of tumor cells and our study reveals that EphA2 stays phosphorylated on Ser897 in the Ephrin B3/EphA2 complex in NSCLC cells of different histology." (PMID 27533087, 2016). "It would therefore be interesting to further analyze Ephrin B3 in whole tumor sections especially at the invasive front of tumors." (PMID 27533087, 2016). "In conclusion, we show that blocking Ephrin B3 expression inhibits NSCLC proliferation-, migration- and invasion capacity which calls for further studies on interference with Ephrin B3 as a possible therapeutic avenue in this tumor malignancy." (PMID 27533087, 2016). "Silencing of EFNB3 through intra-tumoral injection of siRNA coupled to in vivo transfectant efficiently decreases EphrinB3 expression in tumoral cells and significantly delays tumor growth." (PMID 28423606, 2017). "We then aimed to determine if Ephrin-B3 gain of expression observed in GBM could promote tumor growth, both by favoring tumoral cells survival and angiogenesis." (PMID 28423606, 2017). "Thus, in vitro, Ephrin-B3 expression by GBM tumor cells favors endothelial cell survival." (PMID 28423606, 2017). "Given that heterodimers of EphA2 and EGFR do exist in tumor cells, one may speculate that by altering the EphA2 interactome Ephrin B3 may influence such EphA2/EGFR heterodimers and in this way control Akt Ser 129 and EphA2 Ser897, resulting in block of EphA2 mediated invasion/migration signaling." (PMID 27533087, 2016). "Given our in vitro results, we analyzed as to what extent Ephrin B3, Ephrin A1 and EphA2 were expressed in early stage IA-IB NSCLC tumor specimens." (PMID 27533087, 2016). "We previously demonstrated that the low expression of favorable NB genes (EFNB2, EFNB3, EPHB6, NTRK1, CD44 and MIZ-1), as well as that of the tumor growth suppressive gene, EPHA2, in NB cell lines was due to epigenetic silencing." (PMID 24190252, 2014). "CD133-positive cells, isolated from the tumor, expressed stem cell markers including nestin, CD133, Ki67, Sox2, EFNB1, EFNB2, EFNB3, Cav-1, Musashi, Nucleostemin, Notch 2, Notch 4, and Pax6." (PMID 22995409, 2012). "First, we used TMA in which the tumor cores were taken from solid tumor tissue hence we cannot rule out that our results are influenced by heterogenity in Ephrin B3 expression which we do not capture in TMA." (PMID 27533087, 2016). "We found Ephrin B3, Ephrin A1 and EphA2 all to have higher expression in tumor tissue relative to surrounding non-tumorous tissue." (PMID 27533087, 2016). "This suggests ephrin-B3 may contribute to basal signaling dynamics rather than actively driving tumor progression." (PMID 41200151, 2025).
tumor (continued). "We showed here that, in addition, EphA4 cannot be considered as a classical oncogenic growth factors receptor since it may be able to act as a conditional tumor suppressor in absence of Ephrin-B3." (PMID 28423606, 2017). "Whereas EFNB3 showed low expression in cancerous tissues, EFNA2 and EFNA5 expression showed no evident difference between tumor and normal tissues." (PMID 36052169, 2022). "Efnb3 was detected in the plasma membrane of mouse cells at the AOI but not in the unaffected cortex or the tumor core, while human EPHA4 expression was found in the plasma membrane of the IGCs." (PMID 25365423, 2014). "In the TCGA_LIHC cohort, 16 of 120 genes were downregulated in HCC tissue rather than in adjacent non-tumor tissue, and 9 of 16 genes, namely, ALDH8A1, C11orf96, CLYBL, EFNB3, ENG, NPC1L1, PIM3, SEC14L2, and SLC8A1, displayed a significant difference (p < 0.05)." (PMID 33352935, 2020).
cancer (7 papers, 2013 to 2022). A tumor composed of atypical neoplastic, often pleomorphic cells that invade other tissues. "Similarly, EFNB2 and EFNB3 are reported to be highly expressed in different types of cancer cells and are associated with poor prognosis." (PMID 35565468, 2022). "Interfering with expression of EFNB3 in cancer cells can induce apoptosis and disrupt pro-survival networks." (PMID 25754370, 2015). "The expression of EFNB3 was downregulated in multiple cancer types, including LIHC." (PMID 36052169, 2022). "Despite this general qualitative increase in expression, there are quantitative differences: ephrin-B1, B2, and A5 are far more highly expressed in invasive and metastatic samples than in DCIS, and the frequency of ephrin-B3 expression in all cancers seems to be lower than the other ligands." (PMID 34360867, 2021). "Thus, the work presented here support the development of new anti-cancer therapies based on Ephrin-B3-targeting, in high-Ephrin-B3 expressing cancer cases." (PMID 28423606, 2017). "Silencing EFNB3 expression down-regulates AKT in cancer cells." (PMID 25754370, 2015). "Consistent with this, we assessed the mRNA expression levels of SIRT1, EFNB3, and several apoptosis-regulating genes (BIK, CASP3, CASP4, and CASP9) in MCF-7 and MDA-MB-231 cancer cells." (PMID 24489730, 2014). "In addition, the level of EFNB3 in the HCC cells and cancerous tissues was significantly reduced compared with the normal liver cell line L-02 (p<0.05) and the para-carcinoma tissues (p < 0.0001)." (PMID 36052169, 2022).
infection (7 papers, 2012 to 2025). The state of being infected such as from the introduction of a foreign agent such as serum, vaccine, antigenic substance or organism. "All rCedV chimeras expressed the heterologous envelope glycoproteins in infected cells, replicated similarly in comparison to rCedV, and infection tropism was specific for ephrin-B2 and ephrin-B3 as entry receptors." (PMID 37243163, 2023). "Our in vitro study indicated that ephrin B2, but not ephrin B3, was able to restore CedPV infection in the ephrin B2-deficient HeLa cells." (PMID 22879820, 2012). "Taken together, the lack of V and W protein expression and inability to utilize EFNB3 could be suggestive of the failure of CedPV to cause clinical disease in animal infection models." (PMID 29587789, 2018). "Genomic analysis revealed that CedPV was closely related to HeV and NiV, but was distinct in its use of EFNB2, but not EFNB3 for cellular entry, and lack of pathogenicity in animal models of infection." (PMID 29587789, 2018). "Mechanism of the initial infection of NK cells with NiV is not clear at this moment, as there are no reports on ephrin-B3 expression (or lack of thereof) in NK cells." (PMID 22303463, 2012). "However, it is unclear whether the combination of type I IFN induction, lower replication, and lack of ephrin B3 tropism leads to an apathogenic transient CedPV infection." (PMID 30909389, 2019). "Meanwhile, cells expressing sEFN A1 or A5 showed no signs of infection or morphological changes, further confirming EFNB2 and EFNB3 as the primary receptors critical for viral entry, whereas EFNB1 may possess a conditional, auxiliary role in mediating viral entry." (PMID 40872782, 2025).
cardiovascular disease (1 paper, 2023). "EFNB3 has been associated with cardiovascular disease, mostly in blood pressure regulation." (PMID 37626628, 2023).
central nervous system disease (1 paper, 2020). "However, central nervous system disease pathologies, which are the ultimate cause of death in fatal NiV and HeV infection, are likely a consequence of markedly increased and specific expression of ephrin-B3 in multiple brain regions." (PMID 31862858, 2020).
neurodegenerative disease (1 paper, 2024). A disorder of the central nervous system characterized by gradual and progressive loss of neural tissue and neurologic function. "Ephrin-B3 is a promising drug candidate for managing neurodegenerative diseases or traumatic brain injury." (PMID 39640846, 2024).
EFNB3 also shares sentences with these, for which no sentence is quoted: breast carcinoma (2 papers); type 2 diabetes (2); adenocarcinoma (1); astrocytoma (1); atherosclerosis (1); Diabetes (1); endometriosis (1); glaucoma (1); heart failure (1); non-small cell lung carcinoma (1); oligodendroglioma (1); osteosarcoma (1); retinoblastoma (1); Salmonella Infections (1); schizophrenia (1); scoliosis (1); spina bifida (1).